B2M (beta-2-microglobulin)
Diseases named in the same sentence as B2M in open-access papers (continued):
Sharing a sentence is not in itself a finding about the gene and the disease.
renal cell carcinoma (4 papers, 2014 to 2024). "Similarly, in human renal cell carcinoma (RCC) cells, B2M suppressed cell death by activating the PI3K/Akt, ERK, and JNK signaling pathways." (PMID 38743119, 2024).
rheumatoid arthritis (4 papers, 2014 to 2023). A chronic, systemic autoimmune disorder characterized by inflammation in the synovial membranes and articular surfaces. "B2M serum levels have also been reported to correlate with disease activity measures in rheumatoid arthritis; however, no such correlation was found for CSF in the present study which might be due to our low number of study participants." (PMID 30770760, 2019).
schizophrenia (4 papers, 2018 to 2024). A major psychotic disorder characterized by abnormalities in the perception or expression of reality. "Consistent with that, compared to appropriately matched healthy controls, individuals with schizophrenia exhibited higher serum B2M levels." (PMID 38743119, 2024). "The expression of B2M is significant increase in schizophrenia patients." (PMID 29795686, 2018).
amyotrophic lateral sclerosis (3 papers, 2013 to 2025). Amyotrophic lateral sclerosis (ALS) is a neurodegenerative disease characterized by progressive muscular paralysis reflecting degeneration of motor neurons in the primary motor cortex, corticospinal tracts, brainstem and spinal cord. "In amyotrophic lateral sclerosis (ALS), B2M expression is upregulated in motor neurons and appears to support neuronal plasticity, potentially through interactions with synaptic receptors such as PirB." (PMID 40862727, 2025).
B-cell lymphoma (3 papers, 2017 to 2021). "We repeated NK-92 competitive co-culture experiments after disruption of DCAF15, PTPN2, STAT1 and ICAM1 in Daudi cells, a B2M-deficient B-cell lymphoma line." (PMID 31452512, 2019). "The minimal requirement for B-cell lymphoma tumor cells to act like professional antigen presenting cells is cell surface expression of the HLA class I heavy chain-B2M complex and the HLA class II heavy chain dimer." (PMID 28507804, 2017).
bacteremia (3 papers, 2015 to 2025). "As the elevation of the cf-DNA amount may have been caused by bacteremia, the origin of the cf-DNA was determined by qPCR of the plasma cf-DNA using organism-specific primers (mouse B2M and bacterial 16S rDNA)." (PMID 26273139, 2015). "The eight differentially expressed genes (DEGs) as key diagnostic markers for bacterial sepsis: FTH1, B2M, NAMPT, KLF6, SRGN, S100A6, S100A9, and S100A8." (PMID 41303672, 2025). "We speculate that an equivalent molecule to sB2M-9 shed from B2M might be responsible for cell survival during bacteremia in mice." (PMID 27503241, 2016).
carotid atherosclerosis (3 papers, 2013 to 2021). A thickening and loss of elasticity of the walls of carotid arteries that occur with formation of atherosclerotic plaques. "B2M was recently found to be independently and significantly associated with adverse cardiovascular outcomes in patients with prevalent asymptomatic carotid atherosclerosis." (PMID 33467687, 2021).
chronic heart failure (3 papers, 2019 to 2022). "In addition, B2M levels are higher in plasma of patients hospitalized with chronic heart failure and correlate with the severity of cardiorenal failure." (PMID 35439923, 2022).
cutaneous melanoma (3 papers, 2017 to 2021). A primary melanoma arising from atypical melanocytes in the skin. "Furthermore, it has been reported that the pig chromosome 1 contains quantitative trait loci (QTL) for cutaneous melanoma, which were mapped near the B2M gene in the melanoblastoma-bearing Libechov minipig swine model." (PMID 28813459, 2017). "While resistance mechanisms to immunotherapy in cutaneous melanoma have been uncovered, including alterations in JAK1/2, B2M, or STK11, a switch of oncogenic drivers under immunotherapy has not yet been observed." (PMID 34072863, 2021).
diabetic nephropathy (3 papers, 2016 to 2017). "The aggregated results of 2 RCTs suggested that Yiqi Yangyin Huoxue Method showed favorable effects for bringing down beta-2 microglobulin of diabetic nephropathy." (PMID 27313643, 2016). "Yiqi Yangyin Huoxue Method is also a valid complementary and alternative therapy in the management of diabetic nephropathy, especially in improving UAER, serum creatinine, fasting blood glucose, and beta-2 microglobulin." (PMID 28386567, 2017). "Yiqi Yangyin Huoxue Method should be a valid complementary and alternative therapy in the management of diabetic nephropathy, especially on improving UAER, serum creatinine, fasting blood glucose, and beta-2 microglobulin." (PMID 27313643, 2016). "Yiqi Yangyin Huoxue Method should be a valid complementary and alternative therapy in the management of diabetic nephropathy, especially in improving UAER, serum creatinine, fasting blood glucose, and beta-2 microglobulin." (PMID 27313643, 2016). "Current systematic review suggested that Yiqi Yangyin Huoxue Method showed positive effects for diabetic nephropathy on improving UAER, serum creatinine, fasting blood glucose, and beta-2 microglobulin, but not for blood urea nitrogen or PBG." (PMID 27313643, 2016).
hemochromatosis (3 papers, 2009 to 2023). A disorder of iron metabolism characterized by a triad of HEMOSIDEROSIS; LIVER CIRRHOSIS; and DIABETES MELLITUS. "Given that hemochromatosis is a risk factor for extraintestinal infection by enteric Yersinia in humans, we evaluated the colonization of Y. pseudotuberculosis in B2m−/− mice following parenteral inoculation." (PMID 19730693, 2009). "Given that hemochromatosis is a risk factor for disseminated infection by enteric Yersinia in humans, the increased susceptibility of B2m−/− mice to oral inoculation with attenuated Y. pseudotuberculosis may only partially result from the absence of CD8+ T cells." (PMID 19730693, 2009). "Previous experimental data suggested the potential implication of B2M in several diseases, not only in glomerulonephritis and/or AKI but also in hemochromatosis." (PMID 37627907, 2023).
Insulin resistance (3 papers, 2021 to 2025). Increased resistance towards insulin, that is, diminished effectiveness of insulin in reducing blood glucose levels. "Elevated levels of B2M are associated with inflammation and metabolic disorders, indicating its role in the inflammatory processes contributing to insulin resistance and β-cell dysfunction in T2D." (PMID 39926598, 2024).
ischemia (3 papers, 2021 to 2022). A hypoperfusion of the BLOOD through an organ or tissue caused by a PATHOLOGIC CONSTRICTION or obstruction of its BLOOD VESSELS, or an absence of BLOOD CIRCULATION. "Recently, the increased expression of B2M in stressed mouse cardiomyocytes was reported to stimulate a wound healing response in mouse fibroblasts with induced ischemia–reperfusion injury." (PMID 35439923, 2022).
lymphoproliferative disorders (3 papers, 2016 to 2021). "It has been demonstrated in several studies that the elevated expression level of B2M is historically associated with poor outcome in several lymphoproliferative disorders, such as AML, myelodysplastic syndrome, and ALL." (PMID 33777800, 2021).
Lynch syndrome (3 papers, 2019 to 2023). An autosomal dominant hereditary neoplastic syndrome characterized by the development of colorectal carcinoma and a high risk of developing endometrial carcinoma, gastric carcinoma, ovarian carcinoma, renal pelvis carcinoma, and small intestinal carcinoma. "Approximately 15% of all CRC and virtually all patients with Lynch syndrome cancers are dMMR, and one‐third of these will also have a somatic B2M mutation." (PMID 31062389, 2019). "Dramatically elevated HEV densities were observed in B2M-mutant Lynch syndrome CRCs, pointing towards a link between lymphocyte recruitment and immune evasion (median 0.485 vs 0.0885 counts/mm2 in B2M-wild-type tumours, p = 0.0237)." (PMID 31358939, 2019). "While various biomarkers of response have been evaluated in the context of MSI CRC, including B2M and JAK1/2 mutations, TMB, WNT pathway mutations, and Lynch syndrome, with mixed results, liver metastases have been associated with a lack of activity in such strategies." (PMID 37686520, 2023).
malnutrition (3 papers, 2020 to 2022). Inadequate nutrition resulting from poor diet, malabsorption, or abnormal nutrient distribution. "Nutritional deficiency and necrotic conditions also increased the expression of FADS1 2 times compared to B2M (p = 0.004) and 5 times compared to GAPDH (p = 0.004)." (PMID 32392704, 2020).
meningioma (3 papers, 2022 to 2025). A generally slow growing tumor attached to the dura mater. "The genomic profiling of the meningioma metastasis revealed multiple nucleotide variants (MNVs), dominantly truncated variants, caused by Deletion/Insertions (DELINs) at the microsatellite site c.41-48 of the Beta-2-Microglobulin (B2M) gene." (PMID 40725113, 2025). "Then, excluding B2M and ATM, regarding the other mutations found in the other genes, no definitive conclusions can be drawn about their role in the development of meningioma due to the lack of previous evidence." (PMID 40725113, 2025).
multiple sclerosis (3 papers, 2022 to 2023). A progressive autoimmune disorder affecting the central nervous system resulting in demyelination. "More specifically, B2m expression is increased in MOG35–55-induced EAE (experimental validation provided in this study) and in cuprizone-induced EAE brain tissue, as well as multiple sclerosis (MS) lesions." (PMID 36429012, 2022).
non-Hodgkin lymphoma (3 papers, 1993 to 2025). Distinct from Hodgkin lymphoma both morphologically and biologically, non-Hodgkin lymphoma (NHL) is characterized by the absence of Reed-Sternberg cells, can occur at any age, and usually presents as a localized or generalized lymphadenopathy associated with fever and weight loss. "Mutations in the B2M gene (p.L12R) are one of the most common alterations found in various malignancies, including non-Hodgkin’s lymphomas." (PMID 40243506, 2025).
ovarian tumour (3 papers, 2014 to 2022). "Next we examined whether the expression of B2M is associated with the clinicopathological features of patients with epithelial-type ovarian tumours." (PMID 26983758, 2016). "B2M is the regulator of immune system and its significantly higher expression was observed in the presence of ovarian tumor." (PMID 36338962, 2022). "The present study was undertaken to examine the expression of B2M in human epithelial-type ovarian tumours, including benign, borderline and malignant tumours, and to investigate the biological function of B2M in OC cells." (PMID 26983758, 2016). "B2M expression in normal ovarian tissues and epithelia-type ovarian tumours was detected by immunohistochemistry and Western blot, followed by the analysis of association with clinical features." (PMID 26983758, 2016). "Current study examined for the first time the expression of B2M in human different epithelial-type ovarian tumours compared with the normal ovary." (PMID 26983758, 2016). "Targeting B2M, such as using siRNA, may provide a potential therapeutic application for patients with B2M-overexpressing ovarian tumour." (PMID 26983758, 2016). "The current study examined the expression of B2M in ovarian tumours, but whether B2M is involved in tumour cell immune-escape in addition to immunosurveillance in patients with OC will need to be evaluated in subsequent studies." (PMID 26983758, 2016). "However, the expression of B2M in the different types of ovarian tumours is barely reported." (PMID 26983758, 2016). "The positivity of B2M expression was higher in patients with ovarian tumour than in patients without tumour." (PMID 26983758, 2016).
pancreatic adenocarcinoma (3 papers, 2020 to 2024). "Additionally, the immunohistochemical results displayed the overexpression of B2M in patients with pancreatic adenocarcinoma." (PMID 38388766, 2024).
pulmonary TB (3 papers, 2011 to 2025). "Thus, the aim of this study was to assess the relationship between immune activation markers: C-reactive protein (CRP), Beta2 microglobulin (B2M) and Neopterin, disease severity prior to treatment and response to therapy in adult pulmonary TB patients." (PMID 26951717, 2016). "To identify the most stable HKGs for analyzing material from patients with pulmonary TB, we selected eight genes—ACTB, B2M, GAPDH, HPRT1, PPIA, RPL13A, YWHAZ and UBC—that are most commonly employed as reference genes in clinical studies." (PMID 41303702, 2025). "In clinical research—including studies of pulmonary TB—the genes GAPDH, ACTB, B2M or ribosomal RNA genes are most frequently chosen as reference genes." (PMID 41303702, 2025).
rectal cancer (3 papers, 2020 to 2024). A primary or metastatic malignant neoplasm that affects the rectum. "In Antigen processing and presentation, the complex of B2M and HLA-B/C activates down-stream signals, upregulates and enhances T cell immunity, and plays an important role in controlling colon/rectal cancer growth." (PMID 38280998, 2024). "However, in our study, we found B2M as the least stably expressed gene in rectal cancer among the studied group of potential reference genes." (PMID 33457124, 2020). "The genes evaluated for rectal cancer and normal rectal samples in our study included GAPDH, RPNI, PUM1, B2M, and PMM1, which are involved in the process of transcription/translation; other genes are involved in nucleotide metabolism, are a part of the cytoskeleton, etc.." (PMID 33457124, 2020).
sarcoma (3 papers, 2013 to 2025). A usually aggressive malignant neoplasm of the soft tissue or bone. "In total specimens from 81 sarcoma patients have been collected and the extracted DNA quality was assessed by PCR amplification of the human housekeeping gene, beta-2 microglobulin (B2M)." (PMID 23671688, 2013). "(3B) In CSC and native cells from sarcoma, the NormFinder software identified GAPDH, YWHAZ and 18S rRNA as the most stable genes, instead G6PD, RPL13a and B2M were the less stable." (PMID 26894994, 2016).
teratoma (3 papers, 2021 to 2024). A non-seminomatous germ cell tumor characterized by the presence of various tissues which correspond to the different germinal layers (endoderm, mesoderm, and ectoderm). "B2M−/− cyiPSCs formed teratoma containing tissues of all three germ layers 3 months after inoculation into the testicular capsules of immunodeficient mice, indicating that B2M−/− cyiPSCs have pluripotency." (PMID 34182799, 2022).
adenoma (2 papers, 2020 to 2021). A neoplasm arising from the epithelium. "Beta-2-microglobulin (β2M) loss is rarely found in distant metastases or dMMR adenomas and has been associated with improved prognosis, particularly adding prognostic value to the increased CD8+ T cell levels found in LS-CRC." (PMID 34125344, 2021).
AIDS (2 papers, 2016 to 2024). A syndrome resulting from the acquired deficiency of cellular immunity caused by the human immunodeficiency virus (HIV). "However, the precise molecular mechanism underlying the elevated plasma B2M levels in AIDS patients remains unidentified." (PMID 38743119, 2024). "In the early stage of HIV research, serum B2M levels in AIDS patients were found to be significantly higher compared to healthy individuals." (PMID 38743119, 2024). "Subsequent studies confirmed that plasma B2M levels continued to increase during the progression of HIV-infected individuals to AIDS." (PMID 38743119, 2024). "Considering that nearly half of the B2M in plasma originates from lymphocytes, and that lymphocyte activation significantly boosts B2M production, it is reasonable to hypothesize that the heightened B2M levels in AIDS patients result from activated lymphocytes following HIV infection." (PMID 38743119, 2024). "B2M could serve as an independent indicator for predicting the advancement of AIDS, irrespective of the CD4 + T cell count." (PMID 38743119, 2024).
anterior uveitis (2 papers, 2015 to 2022). Inflammation of the iris and anterior chamber of the eye. "The diagnosis of TINU was made clinically in our patient with demonstration of bilateral anterior uveitis, elevated serum and urine beta-2 microglobulin, and otherwise negative workup for other causes of uveitis." (PMID 26446047, 2015). "Second, patients with simultaneous or sequential symptomatic bilateral anterior uveitis that were referred to our center were not routinely tested for urinary beta-2-microglobulin." (PMID 36078924, 2022).
bladder tumors (2 papers, 1993 to 2021). "We have previously reported that a coordinated downregulation of antigen processing machinery genes without any alterations in B2M gene is responsible for HLA-I loss in bladder tumors." (PMID 34298868, 2021). "Lack of inverse correlation between these two parameters came from study of one bladder tumour line (FEN), whose absent class I antigens had been corrected by transfection with beta 2 microglobulin gene." (PMID 8512807, 1993).
breast tumor (2 papers, 2022 to 2024). "As a proof of concept, B2m, Jak1, and Psmb9 single gene KOs were generated using the murine EMT6 breast tumor model to promote PD-1 or PD-L1 ICB resistance." (PMID 38427670, 2024).
cadmium poisoning (2 papers, 2017 to 2022). Poisoning occurring after exposure to cadmium compounds or fumes. "Beta-2-microglobulin (B2M) was first discovered in 1964 in the urine of patients with Wilson’s disease and cadmium poisoning, a histocompatibility complex class I (MHC-I) molecule expressed on almost all nucleated cells." (PMID 35647083, 2022). "Beta-2 microglobulin was first discovered in 1964 in the urine of subjects with Wilson’s disease or cadmium poisoning." (PMID 28664159, 2017).
Canavan disease (2 papers, 2025). A neurodegenerative disorder; its spectrum varies between severe forms with leukodystrophy, macrocephaly and severe developmental delay, and a very rare mild/juvenile form characterized by mild developmental delay. "One study demonstrated that oligodendrocyte progenitor cells derived from a hypoimmunogenic hiPSC line, engineered via B2M and CIITA knockout alone, successfully restored myelination in a Canavan disease animal model, a condition marked by severe demyelination." (PMID 40655027, 2025). "For instance, OPCs derived from B2M/CIITA KO iPSCs were shown to express high levels of CD47, a “do-not-eat-me” signal that inhibits phagocytosis by monocytes and macrophages, potentially facilitating their integration into the demyelinating brain of the Canavan disease." (PMID 40655027, 2025).
cardiac amyloidosis (2 papers, 2022 to 2024). Cardiac amyloidosis is a condition whereby cardiac tissue is infiltrated by amyloid fibrils. "This case report is an intriguing piece of research that has further implicated the role of mutations in beta-2 microglobulin (B2M) as the causal factor in cardiac amyloidosis." (PMID 38152117, 2024).
cervical cancer (2 papers, 2025). A primary or metastatic malignant neoplasm involving the cervix. "ARID1A and B2M mutations may serve as potential biomarkers for predicting treatment outcomes in cervical cancer patients undergoing dCRT." (PMID 40536270, 2025).
co-infection (2 papers, 2021). "Differences in concentrations of serum proteins between TB patients with and without HIV co-infection have not been extensively studied, although concentrations of neopterin and beta-2-microglobulin have both been found to be significantly higher in TB patients with HIV than without." (PMID 33717190, 2021).